CCND1 (cyclin D1)
Diseases named in the same sentence as CCND1 in open-access papers (continued):
Sharing a sentence is not in itself a finding about the gene and the disease.
cervical carcinoma (continued). "A related study reported that both CCND1 and CTCF were identified as significant mutated genes in cervical cancer." (PMID 39623397, 2024). "Corroborating our results, in head and neck, oropharyngeal and cervical cancers associated with HPV, cyclin D1 was down-regulated." (PMID 38742684, 2024). "For example, CCND1 amplification or cyclin D1 expression are associated with HPV infection in oral squamous cell carcinoma and cervical cancer." (PMID 38545846, 2024). "The oncoprotein E6 of HPV can activate the transcription factor eIF4E, and its inhibition in cervical cancer cell lines leads to CCND1 downregulation." (PMID 35468924, 2022). "HeLa human cervical cancer cells have also been reported to develop resistance to butyrate via upregulation of cyclin D1." (PMID 36359211, 2022). "This is because NEAT1 binds to miR-193b in a competitive manner to regulate the expression of CCND1, enhancing radioresistance in cervical cancer." (PMID 36685972, 2022). "CAR efficiently inhibited the growth of cervical cancer cells via arresting the cell cycle at G0/G1 phase and modulated the gene expression of related proteins (p21, p27, cyclin D1 and CDK4)." (PMID 36712982, 2022). "lncRNA NEAT1 was also reported to enhance cervical cancer radioresistance via miR-193b-3p/CCND1 axis." (PMID 35600868, 2022). "In summary, a new regulatory network was found, employing HPV16 E6, miR-2861, and the EGFR/AKT2/CCND1 signaling pathway to syntonize proliferation, apoptosis, and invasion in cervical cancer cells." (PMID 33803022, 2021). "A similar result was noted in CyclinD1 protein expression, confirming that miR-193b regulated CCND1 mRNA expression in cervical cancer cells." (PMID 34178650, 2021). "Then, in order to find and confirm that the transcriptional role of cyclin D1 in cervical cancer, we performed the ChIP-seq and RNA -seq on the C33A cells." (PMID 34335935, 2021). "A combination of bioinformatics algorithms, functional analyses, and xenograft models revealed the pivotal roles of METTL3/miR-193b/CCND1 signaling in cervical cancer aggressiveness." (PMID 34178650, 2021). "In our study, we indicated that miR-193b not only led to a G1 arrest in Hela and Siha cells through CCND1 targeting but also acted to suppress malignant features of cervical cancer in xenograft models." (PMID 34178650, 2021). "SALL4 activates MYC and Cyclin D1 by upregulating the Wnt/β-catenin pathway in cervical cancer cells." (PMID 33947962, 2021). "As one of the cell cycle regulators, CCND1 is upregulated in cervical cancer and has a crucial role in enhancing tumorigenesis." (PMID 34178650, 2021). "In order to find the clinic correlation of cyclin D1, we analyzed the correlation of the cyclin D1 expression levels and prognosis of cervical cancer patients in tissue microarray (TMA) cohort." (PMID 34335935, 2021). "Reintroduction of miR-193b markedly suppressed in vitro and in vivo tumorigenicity of cervical cancer cells through CCND1 targeting." (PMID 34178650, 2021). "al., demonstrated that miR-195-5p is downregulated in cervical cancer serum and tissue samples, and can increase cancer cell invasiveness by regulating the target gene cyclin D1, which can be used as its therapeutic target." (PMID 34482792, 2021). "Here, we found that PRDM4 inhibited cell proliferation and tumor formation in cervical cancer by blocking the cell cycle transition from G0/G1 to S phase by regulating cell cycle checkpoint factors, including p21, p27, Cyclin D1, Cyclin E, and CDK4." (PMID 33846573, 2021).
cervical carcinoma (continued). "We found that cervical cancer patients with high cyclin D1 expression had significant lower probabilities of OS (p=0.022) and tend to lower DFS (p=0.053) in comparison with patients with low cyclin D1 expression in the cytoplasm." (PMID 34335935, 2021). "Reintroduction of miR-193b profoundly inhibits tumorigenesis of cervical cancer cells both in vivo and in vitro through CCND1 targeting." (PMID 34178650, 2021). "Up‐regulation of CDK4 and Cyclin D1 has been elucidated to be indicative of promoting effects induced by the receptor for activated protein kinase C on cervical cancer cell growth." (PMID 33417281, 2021). "IHC staining showed cyclin D1 and Ki-67 protein expression in the cervical cancer tissues compared with that in normal tissues." (PMID 34335935, 2021). "The main discovery of this work is the demonstration that cyclin D1 plays a transcriptional function in cervical cancer cell line C33A by acting at gene promoters." (PMID 34335935, 2021). "CyclinD1 (CCND1) was a vital gene among the 64 predicted target genes given previous studies alluding to its importance in cervical cancer development." (PMID 34178650, 2021). "Collectively, these data indicate that LINC01503 enhances the progression of cervical cancer cells via interaction with miR-615-3p/CCND1 axis." (PMID 34149919, 2021). "LncRNA MALAT1 promotes the proliferation of CasSki cervical cancer cells by diminishing expression of the cell-cycle regulatory proteins cyclin D1, cyclin E, and CDK6." (PMID 32607313, 2020). "The results of this “proof of concept” study support targeting the cyclin D1/CDK4/6 complex for development of new treatments for cervical cancer." (PMID 32429557, 2020). "Consistent with this, BCL10 controls the growth of cervical cancer cells via NF-κB-dependent cyclin D1 regulation in cervical cancer cells." (PMID 31658764, 2019). "BCL10-related signaling controls the growth of cervical cancer cells via NF-κB-dependent cyclin D1 regulation." (PMID 31658764, 2019). "The 5-lipoxygenase inhibitor, NDGA, selectively inhibits the expression of cyclin D1 in pancreatic and cervical cancer cells." (PMID 31759365, 2019). "Our results showed that TMS-TMF-4f decreased p-STAT3 levels and STAT3-mediated anti-apoptotic proteins including cyclin D1, survivin, and c-Myc in both HeLa and CaSki cervical cancer cells." (PMID 31816985, 2019). "All of these three molecules, β-catenin, cyclin D1 and c-Myc, were down-regulated by SOX17 in cervical cancer cells, but β-catenin is the upstream molecule of cyclin D1 and c-Myc in Wnt/β-catenin signaling pathway." (PMID 29970906, 2018). "Taken together, we propose a model for the role of ATXN1 in the development of cervical cancer cells as follows: ATXN1 promotes the growth of cervical cancer cells through the upregulation of cyclin D1 during the early stages of tumor development." (PMID 29212253, 2017). "Together, these results confirm that ATXN1 promotes the proliferation and malignant phenotype of cervical cancer cells by regulating cyclin D1." (PMID 29212253, 2017). "This suggests that the disproportionate gains of CCND1 in the early cervical cancer samples are specific to the role of CCND1 in that tumor type." (PMID 27362268, 2016). "Though EGFR, AKT2, and CCND1 are regulated by multiple factors, out data suggest that miR-2861 exhibits tumor suppressor role by suppressing multiple targets including EGFR, AKT2, and CCND1 in HPV16 positive cervical cancer cells." (PMID 27364926, 2016). "In summary, we delineates a novel regulatory network employing HPV16 E6, miR-2861, and EGFR/AKT2/CCND1 signaling pathway to fine-tune proliferation, apoptosis, and invasion in cervical cancer cells." (PMID 27364926, 2016). "Cucurbitacin D treatment of cervical cancer cells arrested the cell cycle in G1/S phase, inhibited constitutive expression of E6, Cyclin D1, CDK4, pRb, and Rb and induced the protein levels of p21 and p27." (PMID 27824155, 2016).
cervical carcinoma (continued). "Meanwhile, overexpression of EGFR, AKT2, and CCND1 eliminate the effect of miR-2861 on cervical cancer cells." (PMID 27364926, 2016). "We also demonstrated that overexpression of miR-2861 resulted in the suppression of EGFR/AKT2/CCND1 pathway in cervical cancer cells." (PMID 27364926, 2016). "Further, we demonstrated a biological link among HPV16 E6, miR-2861, EGFR, AKT2, and CCND1 in cervical cancer cells." (PMID 27364926, 2016). "The second protein DIF induced cyclin D1 degradation in cervical cancer cell lines and regulated stalk differentiation." (PMID 26308848, 2015). "Recently, we have shown that the human La protein stimulates IRES-mediated translation of the cooperative oncogene CCND1 in cervical cancer cells." (PMID 25520193, 2015). "Association between Cyclin D1 (CCND1) polymorphism and cervical cancer risk are conflicting with published articles." (PMID 25204741, 2014). "In order to elucidate the effects of sgRNA targeting of cyclin D1 on other human cancer cells, we examined cyclin D1 expression in cervical carcinoma Hela cells and osteosarcoma MG-63 cells following the addition of naked sgHT5 and sgH5, using qRT-PCR." (PMID 25437003, 2014). "La also binds to the IRES of cyclin D1 (CCND1) in cervical cancer tissues, and its overexpression correlates with upregulation of cyclin D1 while its depletion leads to a reduction of cyclin D1 levels and a defect in cell proliferation." (PMID 22666083, 2012). "For cervical cancers, the prognostic value of Cyclin D1 was supported by the tight correlation between its overexpression and the clinical grade of cervical cancer." (PMID 20105337, 2010). "Additional experiments in U2OS osteosarcoma and HeLa cervical cancer cells indicated that cyclin D1 was also localized predominantly within the cytoplasmic fraction of these cells." (PMID 16503970, 2006). "Cyclin D1, cyclin E and p27kip1 were also constitutively expressed in C4-I human cervical cancer cells." (PMID 11953870, 2002). "Notably, E7 oncogene stimulates SIX1 expression in cervical intra-epithelial neoplasia and cervical cancer cells and accumulation of cyclin D1 in tumor cells, resulting in tumorigenesis." (PMID 39863145, 2025). "Finally, hsa-miR-2861 functions as a tumor suppressor by targeting the EGFR/AKT2/CCND1 pathway in human papillomavirus type 16 E6-induced cervical cancer." (PMID 41496911, 2025). "Similar results were obtained from other groups, who demonstrated that AGK2 induces growth inhibition in the sub-G0 (pre-G1) phase in glioblastoma cells and in the sub-G0 and G1 phases in cervical cancer cells which were mediated by the decrease in cyclin D1, Cdk4 and Cdk6 expression." (PMID 35406775, 2022). "This may indicate that NEAT1 knockdown regulates the radiosensitivity of cervical cancer through the NEAT1/miR-193b-3p/CCND1 signalling pathway." (PMID 35692795, 2022). "HeLa human cervical cancer cells also show resistance to butyrate via upregulation of cyclin D1." (PMID 34829834, 2021). "Relation among METTL3, miR-193b, and CCND1 in cervical cancer." (PMID 34178650, 2021). "Furthermore, we reported that BCL10 regulates tumor cell growth of cervical cancer cells by regulating the activation of NF-κB-dependent Cyclin D1 signaling." (PMID 34412631, 2021). "We first evaluated the clinic correlation of cyclin D1 through the cervical cancer TMA cohort." (PMID 34335935, 2021). "This understanding of the single molecular pathway, HPV16 E6/miR-2861/EGFR/AKT2/CCND1, may provide a new insight into exploring additional strategies for cervical cancer therapy in the future." (PMID 33803022, 2021). "Cyclin D1 is a potential therapeutic target for cervical cancer." (PMID 34680171, 2021).
cervical carcinoma (continued). "Most cyclin D1 protein are localized in the nucleus of cervical cancer cells." (PMID 34335935, 2021). "In cervical cancer cells, the mRNA stability of Cyclin D1 is increased by HuR overexpression." (PMID 32455577, 2020). "Furthermore, G.A enhances tumor necrosis factor (TNF)-α-induced G1 cell cycle arrest by downregulating cyclin D1 and retinoblastoma phosphorylation in the HeLa cervical cancer cell line." (PMID 30210348, 2018). "Thus, we found that ATXN1 promotes the proliferation and malignant phenotype of cervical cancer cells by regulating cyclin D1." (PMID 29212253, 2017). "We identified the cyclin D1 gene as a downstream target of ATXN1 in cervical cancer cell lines." (PMID 29212253, 2017). "Thus, ATXN1 promotes the growth of cervical cancer cells and the subsequent formation of tumors through the upregulation of cyclin D1." (PMID 29212253, 2017). "We then investigated whether ATXN1 overexpression affected the expression of cyclin D1 in cervical cancer cells." (PMID 29212253, 2017). "For instance, miR-195 expression was significantly decreased in cervical cancer cell lines and overexpression of miR-195 exerted a significant inhibitory impact on the proliferation of cervical cancer cells and induced apoptosis in vitro by targeting cyclin D1." (PMID 28487599, 2017). "Furthermore, we found that EZH2 expression was significantly positively correlated with β-catenin, cyclin D1, and c-myc expression in 24 randomly selected cervical cancer samples." (PMID 27092879, 2016). "This understanding of unique molecular pathway, HPV16 E6/miR-2861/EGFR/AKT2/CCND1, may provide the novel insight into the exploration of additional strategies for cervical cancer therapy in the future." (PMID 27364926, 2016). "Moreover, the expression of signaling molecules of the Wnt/β-catenin signaling pathway, including GSK3β, p-GSK3β, β-catenin, cyclin D1 and c-myc, was detected in the Slug-modified cervical cancer cells and their controls." (PMID 27036045, 2016). "Of course, further experiments will be required to confirm whether the down-regulation of cyclin D1 by Slug in cervical carcinoma cells also occurs through direct degradation by GSK3β at the protein level." (PMID 27036045, 2016). "This study reported for the first time that Slug could inhibit proliferation and tumor formation in human cervical cancer cells by up-regulating p21/p27 and/or down-regulating cyclin D1 via the trans-suppression of Akt1/p-Akt1." (PMID 27036045, 2016). "Therefore, in the Slug-modified cervical cancer cells, cell proliferation and tumor formation should be affected by the cyclin D1 protein through the Wnt/β-catenin signaling pathway via the trans-suppression of the expression of the Akt1/p-Akt1 proteins." (PMID 27036045, 2016). "Interestingly, these results are consistent with our previous data where HGF upregulated cyclin D1 expression in cervical carcinoma cells." (PMID 25888626, 2015). "The CCND1 G870A polymorphism does not show significant differences in genotype distribution among healthy women and the cervical cancer patients." (PMID 23675381, 2013). "In our study we have shown that CCND1 A870A genotype associates with susceptibility to esophageal cancer, but not to cervical cancer." (PMID 23675381, 2013).
cervical carcinoma (continued). "RAMB1 treatment also results in a dose- and time-dependent reduction in the steady state levels of cyclin D1 which could at least partially account for the decrease in cell viability observed in the cervical cancer cell lines." (PMID 21909374, 2011). "Interestingly, the expression of Cyclin D1, a pivotal gene for cervical cancer tumorigenesis, was also found to be reduced in ORAOV1 silenced HeLa cells." (PMID 20105337, 2010). "Interestingly, ORAOV1 is also found to regulate the growth of HeLa cells probably through its effect on Cyclin D1, which is a pivotal regulator in the tumorigenesis of cervical cancer." (PMID 20105337, 2010). "However, their study is one of the very few studies showing reduced cyclin D1 in cervical carcinoma." (PMID 17521451, 2007). "Cyclin D1, which is crucial for promoting cell cycle progression, is constitutively expressed in pancreatic, but also in cervical cancer cells and could – at least in part – be responsible for the transformed phenotype of these cells." (PMID 11953870, 2002). "This justification is coherent with our hypothesis of miR-146a-5p inducing resistance and malignancy, and it is also supported by a recent study that observes the relation between the overexpression of miR-146a-5p, increasing levels of cyclin D1, and the number of S-phase cells in cervical cancer." (PMID 37046799, 2023). "In tune, a study of a human cervical cancer cell line (Hela cells) had previously demonstrated that E2-activated ERβ acted as a negative regulator of cyclin D1 gene transcription and effectively abrogated the ER-α-mediated activation of cyclin D1 expression when both ER subtypes are co-expressed." (PMID 35843988, 2022). "Regarding the mechanism, MA might attenuate the proliferation of cells by downregulating the expression level of MMP-7, β-catenin, cyclin D1, and c-Myc and considerably attenuating apoptotic process in cervical cancer cells through Wnt/β-catenin signaling cascade." (PMID 34421589, 2021). "Expression of cyclin D1 in CIN and cervical cancer was evaluated in comprehensive research on the relationship between the levels of immunohistochemical expression of protein and mRNA of ovarian cancer gene 1 (OVCA1), cyclin D1, and p16 and infection with high-risk human papillomavirus." (PMID 34830452, 2021). "In addition, down regulation of CCND1 may be an important mechanism by which everolimus increases the therapeutic window of paclitaxel in cervical cancers." (PMID 32714651, 2020). "However, in case of cervical cancer risk a non-significant association was reported under the recessive model (GG+GA vs AA: OR = 1.52, 95%CI = 0.60–3.90, P=0.38) with reference to CCND1 polymorphism (rs9344)." (PMID 30361291, 2018). "In addition, NEAT1 could enhance the radio-resistance of cervical cancer by suppressing miR-193b-3p-CCND1 interaction." (PMID 30053878, 2018). "Moreover, a non-significant increased risk for cervical cancer in relation to CCND1 polymorphism was observed in Indian population." (PMID 30361291, 2018). "In addition, it was demonstrated that cyclin D1 depletion could trigger the G2/M arrest of HeLa (human cervical cancer cell) and HEK293 (human embryo kidney cell)." (PMID 29510727, 2018). "Therefore, the activation of the EGFR/AKT2/CCND1 signaling pathway induced by HPV16 E6-deprivated miR-2861 expression in cervical cancer cells may, at least partially, explain the tumor suppression effects of miR-2861 in cervical cancer." (PMID 27364926, 2016).